ATP7A (ATPase copper transporting alpha)
Diseases named in the same sentence as ATP7A in open-access papers (continued):
Sharing a sentence is not in itself a finding about the gene and the disease.
Menkes disease (continued). "Mutations or deletions in the ATP7A gene encoding the Cu-ATPase ATP7A are associated with a fatal childhood disorder, Menkes disease." (PMID 33407701, 2021). "In humans, lack of ATP7A activity caused by a mutation in the ATP7A gene leads to severe metabolic syndrome—Menkes disease." (PMID 33260507, 2020). "ATP7A variants cause X-linked recessive (XLR) Menkes disease, occipital horn syndrome and spinal muscular atrophy." (PMID 32344861, 2020). "Lethal infantile neurodegeneration seen in Menkes disease patients is therefore attributable to ATP7A loss of function." (PMID 31969342, 2020). "Mutations in the copper (Cu)-transporting P-type ATPase ATP7A gene cause three distinct human diseases: Menkes disease (MD), its milder allelic variant occipital horn syndrome (OHS) and a form of X-linked hereditary distal motor neuropathy (dHMNX)." (PMID 31969342, 2020). "ATP7A encodes a copper transporter which regulates intracellular ion levels and has previously been implicated in Menkes disease." (PMID 33151932, 2020). "In hereditary neuropathy, missense mutations in ATP7A occur in a locus that results in distinct neuronal loss without causing the severe copper deficiency characteristic of Menkes disease." (PMID 32294113, 2020). "Menkes disease is an X-linked recessive disorder, caused by mutations in the ATP7A gene coding for the copper-transporting ATPase ATP7A." (PMID 32013126, 2020). "Menkes disease is caused by pathogenic variants in ATP7A at Xq21.1, which encodes a transmembrane protein that mediates copper uptake from the intestine and delivers copper to the developing brain." (PMID 31250568, 2019). "Menkes disease is an X‐linked recessive inherited disease caused by pathogenic variants in ATP7A, which leads to profound copper deficiency." (PMID 31250568, 2019). "The mouse ATP7A protein is encoded by the X-linked Atp7a gene, and among its several reported mutations in mice, one (Atp7amo-ms) results in the mottled phenotype resembling Menkes disease and affects mosaic mutant males." (PMID 32010131, 2019). "The hCtr1-Atox1-ATP7A/B cycle is associated with Menkes’ disease and with Wilson’s disease, in which mutations in ATP7A/B disrupt the homeostatic copper balance, resulting in Cu deficiency or overload, respectively." (PMID 31176065, 2019). "On the other hand, mutations in the human ATP7A gene lead to a neurological disorder called Menkes disease, which usually results in mortality at 3–5 years of age in its classical form." (PMID 32010131, 2019). "Mutations is ATP7A are responsible for Menkes disease, a X-linked recessive disorder characterized by growth retardation, neurodegeneration, and peculiar hair." (PMID 30530920, 2018). "Mutations in ATP7A leads to Menkes Disease, a lethal paediatric multisystemic disorder associated to progressive neurodegeneration." (PMID 30530920, 2018). "ATP7A loss-of-function genetic defects cause three neurological diseases, including Menkes disease (OMIM 309400), occipital horn syndrome (OMIM 304150), and X-linked distal spinal muscular atrophy type 3 (OMIM 300489)." (PMID 28355134, 2017). "Menkes disease (MD) is caused by mutations in ATP7A, encoding a copper-transporting P-type ATPase which exhibits copper-dependent trafficking." (PMID 28389643, 2017). "Two well documented copper metabolism disorders in humans are Menkes disease and Wilson disease which are induced by mutations of genes coding for the copper transport proteins, ATP7A and ATP7B, respectively." (PMID 26861285, 2016). "For example, copper ions are absorbed from small intestine via ATP7A; mutations in ATP7A gene, hence leading to the inhibited absorption of copper ions and the severe copper deficiency in Menkes disease." (PMID 27136532, 2016). "This process is severely affected by mutations in ATP7A gene (Menkes disease), resulting in copper accumulation in intestine." (PMID 27472369, 2016).
Menkes disease (continued). "The low frequency of partial / full gene deletions in ATP7B is surprising given that in the homologous ATP7A, intragenic deletions/duplications account for 22% of all mutations resulting in Menkes disease." (PMID 27992490, 2016). "Mutations in ATP7A result in a fatal, X-linked copper-deficiency disorder in infants known as Menkes disease." (PMID 26747866, 2016). "Insufficient copper supply to LOXs results in loss of skin elasticity and osteoporosis, as seen in Menkes disease and ATP7A−/− and Atox1−/− mice." (PMID 27472369, 2016). "The next step in developing new effective treatments for Menkes disease was to study the possibilities of correcting the mutated ATP7A gene." (PMID 26732058, 2015). "To date, mutations in the ABCP have been associated with cancer chemotherapy drug resistance, atherosclerosis, inflammation, and several other diseases, while disorders linked to ATP7A include Menkes disease and occipital horn syndrome." (PMID 25802476, 2015). "Menkes disease is a multi-systemic copper metabolism disorder caused by mutations in the X-linked ATP7A gene and characterized by progressive neurodegeneration and severe connective tissue defects." (PMID 26732058, 2015). "Mice with mutations in the Atp7a gene, called mottled mutants, are well-established and excellent models of Menkes disease." (PMID 26732058, 2015). "Copper deficiency is associated with Menkes disease, a life-threatening pathology in man, which is due to mutations in the ATP7A gene, resulting in defective functioning of ATP7A." (PMID 25247420, 2014). "In humans, mutations in ATP7A cause Menkes syndrome, which has a broad spectrum of clinical disorders that are related to copper deficiency, including progressive neurodegeneration, connective tissue abnormalities, and kinky, colorless hair." (PMID 24639652, 2014). "In our experiments we used a well characterized mosaic mouse line, representing a model of Menkes disease, which carries a mutation in the Atp7a gene and therefore lacks the ATP7A copper-transporting P-type ATPase." (PMID 25247420, 2014). "In our case the presentation of epilepsia partialis continua can be due to lesions caused by heterozygous mutation, C.1138G>A (p.Val380Met) in the ATP7A gene of Menkes disease." (PMID 25506448, 2014). "ATP7A (the disease gene linked to Menkes syndrome) and ATP7B (the gene that is defective in patients with Wilson's disease) encode two major types of copper exporters." (PMID 24639652, 2014). "Here, we analyzed changes in the systemic iron metabolism using an animal model of Menkes disease: copper-deficient mosaic mutant mice with dysfunction of the ATP7A copper transporter." (PMID 25247420, 2014). "The crucial role of ATP7A in intestinal copper homeostasis is documented by the phenotype of Menkes disease (OMIM 309400), an inherited X-linked dysfunction of ATP7A." (PMID 23963605, 2013). "Atp7a is necessary for copper absorption, as exemplified in patients with Menkes disease and in mice harboring Atp7a mutations, which present with copper loading in enterocytes (and other tissues) and severe systemic copper deficiency." (PMID 23776592, 2013). "Menkes disease is a fatal neurodegenerative disorder in infants caused by mutations in the gene ATP7A which encodes a copper (Cu) transporter." (PMID 22815746, 2012). "The prognosis in Menkes disease is associated with early detection, early initiation of treatment and with the preservation of some ATP7A activity, which is necessary for Cu-His treatment response." (PMID 22992316, 2012). "Underlying the mouse disorder are mutations in the Atp7a gene (the human homologue in Menkes disease is ATP7A), which encodes a copper-transporting ATPase." (PMID 22276220, 2012). "Menkes disease is caused by a mutation in the gene encoding the copper transporter ATP7A that results in severe copper deficiency in the brain." (PMID 23055972, 2012).
Menkes disease (continued). "This fits well with the fact that the brindled mutant mouse (a mouse model for Menkes disease) with a mutated ATP7A gene, has a higher than normal copper accumulation in brain capillaries combined with copper deficiency in the brain." (PMID 23055972, 2012). "Conversely, specific mutations in the ATP7A gene cause Menkes' disease, a copper deficiency disorder, which is associated with impaired copper efflux from enterocytes into the blood and inadequate transport of copper to the brain." (PMID 24278698, 2012). "Duplications in the ATP7A gene are estimated from our material to be the disease causing mutation in 4% of the Menkes disease patients." (PMID 22074552, 2011). "Menkes disease (MD) is an X-linked, multisystemic lethal disorder of copper metabolism caused by mutations in the ATP7A gene." (PMID 21494555, 2011). "The Menkes disease gene is (ATP7A) encodes an enzyme p type ATPase which is required for systemic absorbtion, distribution and metabolism of copper in tissues." (PMID 18801184, 2008). "The most commonly cited disease associated with abnormal copper metabolism is Menkes disease, resulting from a mutation of ATP7A, which is necessary for the coding of Cu-ATPase, required for copper absorption in the intestines and its subsequent passage into circulation." (PMID 40218942, 2025). "In addition to classic Menkes disease, where the function of ATP7A is entirely or almost entirely lost, less deleterious mutations in ATP7A are associated with milder phenotypes, such as occipital horn syndrome and distal motor neuron myelopathy." (PMID 39172219, 2025). "Menkes syndrome is a disorder of copper metabolism caused by variants in the ATP7A gene." (PMID 40689217, 2025). "More than 400 nonsense, missense and insertions/deletions have been identified in the human ATP7a gene; those associated with Menkes disease are within the protein coding sequence and map to the copper associated domains, ATPase or transmembrane domains in particular." (PMID 40678754, 2025). "Menkes disease is an X-chromosome-linked disorder, caused by missense mutations or chromosomal rearrangements in the ATP7A gene that lead to inactivation of the Cu transporter ATP7A." (PMID 39172219, 2025). "The patchy coat color suggested X-linkage, and we surmised that the best X-linked candidate gene might be Atp7a, a trans-Golgi copper transporter mutated in Menkes disease in humans (OMIM 309400)." (PMID 40678754, 2025). "ATP7A gene mutation occurs in Menkes disease, which leads to dysfunction in copper homeostasis." (PMID 40291937, 2025). "Inactivity of the ATP7A copper transporter therefore results in severe copper deficiency which particularly affects the brain, and accounts for the severest neurological phenotypes in Menkes disease." (PMID 38141875, 2024). "The majority of variants identified in ATP7A have been identified in patients with Menkes disease." (PMID 38141875, 2024). "ATP7A is an ATPase copper transporting alpha protein which causes Menkes syndrome." (PMID 37563452, 2024). "Moreover, Menkes disease patient serum lactate levels (with ATP7A genetic deficiency) were substantially elevated, implying a potential connection between lactate and human copper metabolism." (PMID 39691393, 2024).
Menkes disease (continued). "Copper maldistribution in some tissues is associated with low copper levels in the heart, liver, muscle, skin, and connective tissues that are causally related to mutations in the ATP7A gene of Menkes disease, whereby ATP7A represents an ATPase that transports copper." (PMID 38731973, 2024). "Their deficiency due to gene mutations is at the basis of WD (mutations of the ATP7B gene) and Menke’s disease (mutated ATP7A gene), two disorders characterized by severe neuropathological deficits and by neuropsychiatric symptoms in a high percentage of patients who are affected." (PMID 38928192, 2024). "The identified novel ATP7A mutation associated with Menkes disease expands the ATP7A gene spectrum." (PMID 36936426, 2023). "WES analysis of the proband and both parents identified the novel de novo ATP7A variant c.3642_3649dup (p.Ala1217Aspfs*2), leading to a diagnosis of Menkes disease, and the co-occurrence of homozygous variant c.1057C>T (p.Arg353Cys) in the ACY1 gene causative of Aminoacylase-1 deficiency." (PMID 36936426, 2023). "Due to the role of ATP7A in copper import, genetic mutations in ATP7A cause the neurological condition Menkes disease, in which patients develop a severe copper deficiency leading to symptoms of neurodegeneration, developmental delays and accelerated mortality." (PMID 37905492, 2023). "Whole-exome sequencing analysis (WES) revealed the novel de novo variant c.3642_3649dup (p.Ala1217Aspfs*2) in the ATP7A gene, leading to a diagnosis of Menkes disease, and the simultaneous presence of the homozygous ACY1 variant c.1057C>T (p.Arg353Cys) causative of Aminoacylase-1 deficiency." (PMID 36936426, 2023). "Menkes’ disease is an X-linked recessive disorder, fatal to male infants, in which the dysfunction of ATP7A leads to reduced Cu availability in tissues, causing growth retardation, hypotonia, kinky, brittle hair (pili torti), deterioration of the nervous system, and severe intellectual disability." (PMID 38139406, 2023). "Mutations in the ATP7A gene are associated with Menkes disease and occipital angle syndrome." (PMID 37799137, 2023). "ATP7A is widely recognized as a copper-transporting ATPase due to mutations in its gene that cause impaired copper transport and further cause the neurological genetic disorder Menkes disease." (PMID 36338988, 2022). "Menkes disease is a neurological disorder caused by mutations in ATP7A, an X-linked gene." (PMID 36818726, 2022). "Menkes disease (MD), a lethal X-linked recessive syndrome that is characterized by generalized alterations in copper transport and metabolism, is linked to pathogenic variants in the ATPase copper transporting α (ATP7A) gene, which maps to Xq21.1." (PMID 34069220, 2021). "Similarly, Menkes disease, an X-linked recessive disorder, is a result of mutation in the ATP7A gene; the purpose of ATP7A is to code for copper regulation and copper absorption from food." (PMID 33430181, 2021). "In Menkes disease, an X-linked disorder associated with almost 300 loss of function mutations of the gene encoding ATP7A, whose phenotype includes systemic copper deficiency and pleiotropic CNS manifestations, there is cerebrovascular copper accumulation and low brain copper levels." (PMID 34439901, 2021). "Menkes disease (MD) is a rare and often lethal X-linked recessive syndrome, characterized by generalized alterations in copper transport and metabolism, linked to mutations in the ATPase copper transporting α (ATP7A) gene." (PMID 34069220, 2021). "For example, mutations in the ATP7A gene, encoding a copper transporter responsible for copper transport from enterocytes to blood, lead to copper deficiency and development of Menkes disease characterised by progressive neurodegeneration and connective tissue disturbances." (PMID 33668157, 2021).
Menkes disease (continued). "Due to the requirement of ATP7A for the transport of copper through the basolateral membrane of intestinal epithelial cells, in Menkes disease, a copper deficiency is present in blood, kidney, liver and brain, while copper deposits are present in the intestinal enterocytes." (PMID 32013126, 2020). "To examine the role of ATP7A protein in the process of spermatogenesis, we used mice with the mosaic mutation (Atp7amo-ms) belonging to the group of mottled mouse models, recognized as animal models of Menkes disease." (PMID 33260507, 2020). "In Menkes’ disease, there is a deficiency of copper in the blood, kidneys, liver, and brain due to the need of ATP7A to transport copper through the basolateral membrane of intestinal epithelial cells, while copper deposits are present in intestinal enterocytes." (PMID 33291628, 2020). "In addition, in two patients (patients 3,5) the translocations disrupted NFIA and ATP7A, which are a known cause of developmental delay and Menkes disease, respectively." (PMID 32344861, 2020). "There are over 370 ATP7A mutations causing Menkes disease (Tümer, 2013)." (PMID 31969342, 2020). "The growing knowledge about the dysfunction of these proteins in Wilson and Menkes diseases should definitely help to determine how Cu and Pt metabolic pathways might be manipulated to suppress ATP7A/B-associated oncogenic processes." (PMID 31540259, 2019). "For example, impaired satellite cells due to loss of ATP7A function in Menkes disease may impair muscle development leading to hypotonia." (PMID 29333545, 2018). "Mutations in ATP7A, result in the X-linked recessive disorder Menkes disease." (PMID 28459846, 2017). "If we were to subtract the cost of every single gene test from C1's cost analysis (cost for batten screen, CDKL5, SCN1A gene sequencing, Rett gene sequencing, ATP7A for Menkes disease, and X-linked mental retardation-sequencing of a panel of 7 genes), the excess cost would have still been $13,055." (PMID 27243033, 2016). "Menkes disease, involving ATP7A, is a fatal neurodegenerative disorder of copper deficiency." (PMID 26747866, 2016). "Loss of ATP7A activity is associated with fatal Menkes disease and various other pathologies." (PMID 27226607, 2016). "Mouse models of Atp7a dysfunction are of particular importance for medical studies because mutations in the homolog human gene, ATP7A lead to the metabolic syndrome called Menkes disease, a fatal metabolic syndrome in humans." (PMID 26732058, 2015). "Furthermore, high conservation of Cu-ATPases between mammals and fruit fly permits the correction of the Cu hyper-accumulation phenotype of cultured fibroblasts from a Menkes disease patient carrying a null ATP7A mutation, by the expression of DmATP7." (PMID 26732058, 2015). "Its essentiality is demonstrated by Menkes disease, an X-linked copper deficiency disorder characterized by defects in nervous-, cardiovascular- and skeletal systems, and is caused by mutations in the ATP7A copper transporter." (PMID 22900086, 2012). "In mice mutations in the Atp7a gene also lead to disturbances in copper metabolism, and the severity of the phenotype is dependent on the specific mottled mutation in similarity to what is observed for patients with Menkes disease." (PMID 22815746, 2012). "Menkes disease (MD) is caused by mutations in the ATP7A gene." (PMID 21494555, 2011). "Menkes disease, also referred to as Menkes kinky hair disease, is a recessive X-chromosome-linked hereditary disease in humans caused by mutations (serine to proline) in a gene encoding the copper transport protein ATP7A, which lead to defective copper metabolism." (PMID 39858530, 2025). "Menkes disease (MD) and WD are genetic disorders associated with copper metabolism, characterized by mutations in the ATP7A or ATP7B genes, respectively." (PMID 40808953, 2025).